OR6B2 (olfactory receptor family 6 subfamily B member 2)
Description:
Odorant receptor.
Synonyms: OR6B2P; OR2-1
Tractability: Antibody: its Gene Ontology location is reachable by antibodies, with high confidence; UniProt places it where antibodies can reach, with medium confidence; UniProt predicts a signal peptide or a membrane-spanning region; the Human Protein Atlas places it where antibodies can reach.
Gene: Protein-coding gene on chromosome 2 (240,029,491 to 240,030,429, reverse strand). Ensembl gene ENSG00000182083.
Subcellular location: Cell membrane
Subcellular location (Human Protein Atlas): Plasma membrane; Cytosol
Pathways (Reactome):
Sensory Perception: Expression and translocation of olfactory receptors
Gene Ontology:
Molecular function: odorant binding; olfactory receptor activity; G protein-coupled receptor activity
Biological process: sensory perception of smell; detection of chemical stimulus involved in sensory perception of smell; G protein-coupled receptor signaling pathway
Cellular component: plasma membrane; membrane
Genetic constraint (gnomAD): Missense variants: 113 observed, 137.25 expected, observed/expected ratio (o/e) 0.82, 90% interval 0.71 to 0.96. Synonymous variants: 64 observed, 59.62 expected, observed/expected ratio (o/e) 1.07, 90% interval 0.88 to 1.32.
Homologues: Orthologues: macaque OR6B2 (94% identical), rat Or6b3 (87% identical), mouse Or6b3 (87% identical), mouse Or6b2 (86% identical), mouse Or6b2b (86% identical), rat Or6b2b (85% identical), dog OR6B2 (83% identical), dog OR6B2D (83% identical), dog OR6B2C (82% identical). Paralogues in human: OR6B3 (94% identical), OR6P1 (53% identical), OR6Q1 (47% identical), OR5A2 (47% identical), OR8D4 (46% identical), OR8I2 (46% identical), OR5A1 (46% identical), OR8U1 (46% identical), OR5AS1 (45% identical), OR8H1 (45% identical), OR5AP2 (45% identical), OR11L1 (45% identical), and 84 more.
Diseases named in the same sentence as OR6B2 in open-access papers:
OR6B2 is named in the same sentence as 1 disease in open-access papers, as found by Europe PMC text mining. Sharing a sentence is not in itself a finding about the gene and the disease.
OR6B2 shares sentences with these, for which no sentence is quoted: cancer (1 paper).